SDC1 (syndecan 1)
Diseases named in the same sentence as SDC1 in open-access papers (continued):
Sharing a sentence is not in itself a finding about the gene and the disease.
COVID-19 (continued). "In contrast to the previous and current findings in COVID-19 patients, we only detected moderately increased levels of calprotectin among the other parameters (NETs, neopterin, and syndecan-1) tested in COVID-19 convalescent blood donors in Oslo." (PMID 38672123, 2024). "We found significantly higher syndecan-1 concentrations in patients with confirmed infectious pathology (including COVID-19), but when comparing strictly to the relevant C-reactive protein (CRP), the association was no longer significant (p = 0.234)." (PMID 37109427, 2023). "With the emergence of COVID-19, studies evaluated the role of syndecan-1 as a biomarker in distinguishing COVID-19 patients from controls, the severity of COVID-19, and its role as a prognostic marker." (PMID 37542221, 2023). "The high number of studies evaluating syndecan-1 levels in COVID-19 compared to other biomarkers is the strength of this study." (PMID 37542221, 2023). "First, we were unable to perform meta-analyses to compare different severities of COVID-19 in addition to evaluating syndecan-1 role in predicting ICU admission following SARS-CoV-2 infection." (PMID 37542221, 2023). "In this systematic review and meta-analysis, we present the findings from studies that reported syndecan-1 levels in COVID-19 patients or convalescents and compared them with controls." (PMID 37542221, 2023). "All in all, syndecan-1 is a useful biomarker of glycocalyx damage and can be used to detect endothelial dysfunction in several populations including COVID-19 patients." (PMID 37542221, 2023). "Circulating syndecan-1 level can be used as a biomarker of endothelial dysfunction in COVID-19, as it was increased in COVID-19 patients and was higher in more severe instances of the disease." (PMID 37542221, 2023). "Pilot studies have shown that the core protein syndecan-1 and heparan sulphate levels are elevated in COVID-19, although the predictive power increases with disease severity or during disease progression." (PMID 37629312, 2023). "In this meta-analysis of six studies, we found significantly higher syndecan-1 concentration in patients with COVID-19 compared to healthy control subjects (SMD 1.53, 95% CI 0.66 to 2.41, p-value < 0.01)." (PMID 37542221, 2023). "We found no studies evaluating the therapeutic effectiveness of targeting syndecan-1 in COVID-19 patients." (PMID 37542221, 2023). "Meta-analysis of these studies revealed that patients who died from COVID-19 had significantly higher levels of syndecan-1, compared with those who survived (SMD 1.22, 95% CI 0.10 to 2.33, P = 0.03)." (PMID 37542221, 2023). "First, in line with our results, almost all studies comparing syndecan-1 levels between COVID-19 cases and healthy control subjects found higher levels in COVID-19 patients compared to healthy individuals." (PMID 37542221, 2023). "Meta-analysis of syndecan-1 levels in COVID-19 compared with healthy control subjects revealed that patients with COVID-19 had significantly higher syndecan-1 levels (SMD 1.53, 95% CI 0.66 to 2.41, P < 0.01)." (PMID 37542221, 2023). "Plasma levels of a proteoglycan, syndecan-1, are found to be significantly elevated in patients with COVID-19, but its roles in assessing disease severity and predicting long-term outcome are not fully understood." (PMID 36675479, 2023). "Longitudinal analysis demonstrated that while the levels fluctuated during hospitalization in all patients, plasma syndecan-1 levels were persistently elevated from baseline in critical COVID-19 patients." (PMID 36675479, 2023). "In fact, numerous studies have investigated syndecan-1 levels in hospitalized COVID-19 patients, as well as in COVID-19 convalescence." (PMID 37542221, 2023). "They found higher syndecan-1 levels in critical COVID-19 patients compared to severe COVID-19 cases (P < 0.05)." (PMID 37542221, 2023).
COVID-19 (continued). "In vivo evidence suggests that COVID-19 patients with severe symptoms showed endothelial glycocalyx disruption and syndecan-1 (SDC-1) secretion." (PMID 37626992, 2023). "In COVID-19 patients, we observed increased plasma MPO levels, MPO activity, syndecan-1 and glypican-1 concentrations to be associated with severe disease." (PMID 37147421, 2023). "Compared to other inflammatory conditions, syndecan-1 levels are higher in severe COVID-19 patients compared to septic shock patients with bacterial pneumonia." (PMID 37175942, 2023). "They found higher plasma syndecan-1 levels in patients with severe COVID-19 (148.5 [103.3–203.3] ng/ml) compared to mild COVID-19 cases (63.8 [49.0–138.6] ng/ml; P < 0.05) and healthy control subjects (48.0 [44.9–73.3] ng/ml; P < 0.005)." (PMID 37542221, 2023). "Future studies are warranted to evaluate the effect of lowering syndecan-1 levels by specific medications in the disease course of COVID-19." (PMID 37542221, 2023). "In agreement, we demonstrated increased syndecan-1 and glypican-1 (albeit lower than syndecan-1 levels) shedding in COVID-19 patients, and protein concentrations were the highest in severe cases." (PMID 37147421, 2023). "We conclude that plasma levels of syndecan-1 on admission and at other time points were significantly elevated in patients with severe to critical COVID-19 compared with the healthy controls." (PMID 36675479, 2023). "The present study demonstrates the role of longitudinal assessment of plasma levels of syndecan-1 in predicting 60-day mortality in patients with COVID-19." (PMID 36675479, 2023). "Higher syndecan-1 levels were shown in patients who died from COVID-19 and those with the need for mechanical ventilation." (PMID 37542221, 2023). "Plasma syndecan-1 levels were higher in patients with COVID-19 than in other CAP groups, indicative of enhanced endothelial glycocalyx degradation." (PMID 35660785, 2022). "Plasma syndecan-1 was significantly higher in COVID-19 patients classified as “critical” compared to those in the “severe” category; a difference that persisted for 14 days of ICU admission." (PMID 35872762, 2022). "On the other hand, there was a strong correlation between the nitrite/nitrate values and the concentration of syndecan-1, suggesting a close relationship between endothelial damage and COVID-19 severity." (PMID 36556051, 2022). "Changes in serum syndecan-1, thrombomodulin, and angiogenic factor concentrations were analysed during the first 24 h and 10 days after COVID-19 hospitalisation in patients with high-flow nasal oxygen or mechanical ventilation." (PMID 35372407, 2022). "Compared with healthy control subjects, COVID-19 positive patients had higher plasma von Willebrand factor, and glycocalyx-degradation products (chondroitin sulfate and syndecan-1)." (PMID 35872762, 2022). "In COVID-19, reports of syndecan-1 increase are related to disease severity and have been suggested as an assessment of the clinical course of the patient." (PMID 35372407, 2022). "We found that Hyal and SDC1 were increased in COVID-19 patients and these markers correlated with disease severity." (PMID 34792686, 2021). "Inflammation-induced degradation of the glycocalyx, which is measured by the glycocalyx biomarkers syndecan-1 (SDC-1), sP-selectin and hyaluronic acid, contribute to microvascular pathology in COVID-19 patients." (PMID 33504351, 2021). "Relative to the controls, the patients with severe COVID-19 had significantly higher concentrations of biomarkers for glycocalyx shedding (endocan and syndecan-1) and endothelial injury (vWF)." (PMID 34214123, 2021). "Studies with more patients are required to examine the association between Syndecan-1 and the disease state of COVID-19, and the relationship between Syndecan-1 and the mechanism that leads to severe conditions of COVID-19 is required as well." (PMID 34861818, 2021).
COVID-19 (continued). "Here, we present the case of a COVID-19 patient with ARDS in whom serum SDC-1, a component of glycocalyx, was measured over time, and examine the association of SDC-1 as a reflection of the disease state of COVID-19 in relation to endothelial injury." (PMID 33504351, 2021). "The exact mechanism responsible for the increased serum level of Syndecan-1 during the progression of COVID-19 is poor understood." (PMID 34861818, 2021). "In this study, we measured two endothelial damage biomarkers (Syndecan-1 and thrombomodulin) in sera obtained from COVID-19 patients who were admitted to an ICU in Wuhan, China." (PMID 34861818, 2021). "In this prospective cohort study, we measured the GAC components syndecan-1 (SDC1) and hyaluronan (Hyal) along with inflammatory cytokines in 12 hospitalized COVID-19 patients and 8 healthy controls (HC)." (PMID 34792686, 2021). "COVID-19 patients with high levels of Syndecan-1 develop more serious endothelial damage and inflammatory reactions, and have increased mortality." (PMID 34861818, 2021). "In this study, we found that inflammatory biomarkers (IL-6 and TNFα) and GAC markers (Hyal and SDC1) were elevated in hospitalized COVID-19 patients compared with HC." (PMID 34792686, 2021). "Syndecan-1 (SDC-1), a marker of endothelial glycocalyx degradation was found in COVID-19 patients." (PMID 41415584, 2025). "In COVID-19 there has been a growing number of studies on the prognostic ability of syndecan-1." (PMID 37175942, 2023). "At all timepoints, GSEA suggested a pronounced activation of neutrophils, platelets and coagulation in COVID-19, but also enrichment of the Wound healing GO term (including genes IGF1 and SDC1), suggesting ongoing immune activation by Danger-Associated Molecular Patterns (DAMPs)." (PMID 37365222, 2023). "Elevated levels of syndecan-1 exist in COVID-19 patients compared to healthy controls." (PMID 37175942, 2023). "Also, we reviewed the possible changes in syndecan-1 levels with regard to COVID-19 complications such as ICU admission and death." (PMID 37542221, 2023). "Three studies compared syndecan-1 levels between alive and dead patients with COVID-19." (PMID 37542221, 2023). "Eleven studies evaluated syndecan-1 levels in patients with COVID-19 and healthy individuals." (PMID 37542221, 2023). "Regarding convalescents, there were controversies in the studies, so, among the three studies we used in the meta-analysis, one study reported significantly higher syndecan-1 levels while the other reported significantly lower syndecan-1 levels in patients with COVID-19." (PMID 37542221, 2023). "Two studies compared syndecan-1 levels between different severities of the COVID-19." (PMID 37542221, 2023). "In addition, inclusion of the PC gene SDC1 in the final gene list distinguishing COVID-19 from non-COVID-19 ICU patients is in agreement with our previous work in which PC enrichment was the major difference in these cohorts." (PMID 36902333, 2023). "Moreover, patients who died from COVID-19 had higher syndecan-1 levels compared with survivors (SMD 1.22, 95% CI 0.10 to 2.33, P = 0.03)." (PMID 37542221, 2023). "In this systematic review and meta-analysis, we found higher levels of syndecan-1 in patients with COVID-19 compared to healthy control subjects through meta-analysis, in addition to higher syndecan-1 levels in higher severities of COVID-19 based on two individual studies." (PMID 37542221, 2023). "At acute and convalescent phases, COVID-19 positive subjects had significantly higher syndecan-1 [acute (p < 0.01); convalescent (p < 0.05)] and glypican-1 [acute and convalescent both p < 0.01)] breakdown compared with controls [both proteins below limit of detection]." (PMID 37147421, 2023). "Six studies evaluated the prognostic role of syndecan-1 in patients with COVID-19." (PMID 37542221, 2023). "In fact, syndecan-1 continued to increase over the 7 days that COVID-19 patients were tested." (PMID 35872762, 2022).
COVID-19 (continued). "Syndecan-1 has potential for use as a marker for progression or severity of COVID-19." (PMID 34861818, 2021). "Furthermore, COVID-19 patients were divided into high and low Syndecan-1 groups according to the cut-off value." (PMID 34861818, 2021). "Here, we report that syndecan-1, a component of endothelial glycocalyx, may reflect the disease state of COVID-19 related to endothelial injury." (PMID 33504351, 2021). "Recent studies reported the levels of Syndecan-1 and thrombomodulin in COVID-19 patients." (PMID 34861818, 2021). "Overall, our results suggest that Syndecan-1 could be used as a biomarker for monitoring COVID-19 progression, and possibly that prevention of glycocalyx destruction could be a new method for treatment of COVID-19." (PMID 34861818, 2021). "Additionally, severe COVID-19 cases exhibit increased circulation of EG proteoglycans (syndecan-1, HS, and hyaluronan) and markers of endothelial injury (vascular endothelial growth factors, angiopoietin-1, and soluble thrombomodulin), compared to non-severe and uninfected cases." (PMID 38753622, 2024). "In this study, we focused on SDC-1, a component of the glycan chain expressed on the surface of the vascular endothelium, as a potential biomarker for assessing the severity of COVID-19 since endothelialitis is thought to be involved in the pathogenesis of severe COVID-19." (PMID 38907229, 2024). "This study investigated syndecan-1 (SDC-1), a marker of endothelial damage, as a potential prognostic factor for COVID-19, focusing on the Japanese population, which is known for its aging demographics and high prevalence of comorbidities." (PMID 38907229, 2024). "Studies have confirmed that patients infected with COVID-19 can produce inflammation-induced degradation of the GAC layer of endothelial cells, and SDC1 can be used as an important parameter to assess GAC damage." (PMID 37007526, 2023). "We studied patients with RT-PCR confirmed COVID-19 pneumonia, patients with COVID-19 Acute Respiratory Distress Syndrome (ARDS) and healthy controls (wildtype, n=20 in each group) and measured syndecan-1, heparan sulfate and hyaluronic acid." (PMID 36776845, 2023). "It has been reported that the plasma levels of syndecan-1 and HA significantly increased in COVID-19 patients, and the degradation of the EGL would deteriorate the conditions of COVID-19 patients." (PMID 35741101, 2022). "Plasma samples from 57 subjects at < 48 h of COVID-19 hospitalization, and 20 matched controls were interrogated for the levels of six BIMs—including GFAP, S100B, Syndecan-1, UCHLI, MAP2 and NSE, two EIMs—including sICAM1 and sVCAM1." (PMID 34838058, 2021). "Our data indicate increased SDC-1 and continuous changes in SDC-1, a core protein of the glycocalyx whose degradation indicates endothelial injury in critical COVID-19 patients relative to severe COVID-19 patients at 2 weeks of admission." (PMID 34399775, 2021). "To investigate the effects of COVID-19 on BIMs, we examined systemic levels of six previously validated BIMs—MAP2, NSE, GFAP, S100B, Syndecan-1 and UCHL1." (PMID 34838058, 2021). "In mechanically ventilated COVID-19 patients, Stahl and colleagues found evidence of endothelial GAC disruption with elevated Tie2 and SDC1 compared with HC." (PMID 34792686, 2021). "Like previous findings, COVID-19 plasma treatment on primary endothelial cells induced soluble EG shedding, however, differences in syndecan-1 shedding but not glypican-1 disruption was more prominent between COVID-19 severity." (PMID 37147421, 2023). "We performed a meta-analysis of syndecan-1 levels between COVID-19 convalescents and patients without prior COVID-19 infection." (PMID 37542221, 2023). "Although antirheumatic medications including methotrexate and tumor necrosis factor (TNF) alpha inhibitors reduced syndecan-1 levels, no studies evaluated the effectiveness of syndecan-1 lowering in COVID-19." (PMID 37542221, 2023).
COVID-19 (continued). "Meta-analysis was performed for comparison of syndecan-1 levels in COVID-19 patients with and without the need for mechanical ventilation." (PMID 37542221, 2023). "During illness, syndecan-1 is degraded by several matrix metalloproteinases and ADAM17 and may be a biomarker candidate for the diagnosis and prognosis of COVID-19." (PMID 37542221, 2023). "In COVID-19 ARDS, syndecan-1 increased IL-6, which was significantly higher than in pneumonia." (PMID 36776845, 2023). "Serum syndecan-1 concentrations within the first day of ICU admission were significantly higher in non-surviving COVID-19 patients compared to survivors." (PMID 35872762, 2022). "Here, we report that syndecan-1 (SDC-1), a component of the endothelial glycocalyx, may be a biomarker of severity classification for COVID-19 related to endothelial injury." (PMID 34399775, 2021). "Demographic, clinical, and laboratory data, and outcomes were compared between survivors and non-survivors COVID-19 patients, and between patients with high and low serum Syndecan-1 levels." (PMID 34861818, 2021). "Thus, measuring syndecan-1 as a biomarker is not useful in distinguishing past SARS-CoV-2 infection from patients without a history of COVID-19." (PMID 37542221, 2023). "Analysing a subset of acute and convalescent COVID-19 plasma, 10 from severe and 15 from non-severe COVID-19 cases, and 9 from pre-COVID-19 controls, we determined MPO levels, MPO activity and soluble EG proteins (syndecan-1 and glypican-1) levels by enzyme-linked immunosorbent assay." (PMID 37147421, 2023). "The same study showed that plasma concentrations of HA were significantly higher in both non- and ventilated COVID-19 patients compared to controls, while syndecan-1 was higher in ventilated COVID patients compared to both non-ventilated COVID-19 patients and controls." (PMID 35872762, 2022). "In line with our results, glycocalyx shedding has been also recently reported in adult patients with COVID-19 who presented elevated plasma or serum syndecan-1 levels, as compared to healthy subjects or non-COVID-19 ICU patients, that remained elevated up to 7 days after admission." (PMID 35347344, 2022). "Even in convalescent COVID-19 patients who were never hospitalized, a persistent increase in serum syndecan-1 concentrations compared to healthy controls was found at a mean of 88 days post symptom onset, and was not significantly different from currently hospitalized COVID-19 patients." (PMID 35872762, 2022).